MIR5687 (microRNA 5687)
Synonyms: hsa-mir-5687
Gene: MicroRNA gene on chromosome 5 (55,508,850 to 55,508,926, reverse strand). Ensembl gene ENSG00000265135.
Homologues: Orthologues: chimpanzee MIR5687 (100% identical).